TMEM182 (transmembrane protein 182)
Description:
Negatively regulates myogenesis and skeletal muscle regeneration via its association with ITGB1 (By similarity). Modulates ITGB1 activation by decreasing ITGB1-LAMB1 interaction and inhibiting ITGB1-mediated intracellular signaling during myogenesis (By similarity).
Synonyms: FLJ30294
Tractability: Antibody: UniProt places it where antibodies can reach, with medium confidence; UniProt predicts a signal peptide or a membrane-spanning region; its Gene Ontology location is reachable by antibodies, with medium confidence.
Gene: Protein-coding gene on chromosome 2 (102,736,905 to 103,019,900, forward strand). Ensembl gene ENSG00000170417.
Subcellular location: Cell membrane
Subcellular location (Human Protein Atlas): Nucleoplasm; Vesicles
Gene Ontology:
Molecular function: protein binding
Biological process: myotube cell development involved in skeletal muscle regeneration; myotube differentiation involved in skeletal muscle regeneration; negative regulation of myoblast differentiation; negative regulation of myoblast fusion
Cellular component: plasma membrane; membrane
Genetic constraint (gnomAD): Loss-of-function variants: 20 observed, 26.62 expected, observed/expected ratio (o/e) 0.75, 90% interval 0.53 to 1.09. The upper end of that interval is the gene's LOEUF score, 1.09, which puts it in group 4 of 6, group 1 being the genes least tolerant of losing a copy. Missense variants: 276 observed, 286.62 expected, observed/expected ratio (o/e) 0.96, 90% interval 0.87 to 1.06. Synonymous variants: 109 observed, 108.33 expected, observed/expected ratio (o/e) 1.01, 90% interval 0.86 to 1.18.
Homologues: Orthologues: chimpanzee TMEM182 (99% identical), macaque TMEM182 (98% identical), pig TMEM182 (95% identical), dog TMEM182 (94% identical), rabbit TMEM182 (94% identical), mouse Tmem182 (89% identical), guinea pig TMEM182 (83% identical), rat Tmem182 (76% identical), tropical clawed frog tmem182 (61% identical), zebrafish tmem182a (50% identical), zebrafish tmem182b (36% identical).
Diseases named in the same sentence as TMEM182 in open-access papers:
TMEM182 is named in the same sentence as 8 diseases in open-access papers, as found by Europe PMC text mining. Sharing a sentence is not in itself a finding about the gene and the disease. The quoted sentences say what the papers report.
glaucoma (3 papers, 2013 to 2019). Increased pressure in the eyeball due to obstruction of the outflow of aqueous humor. "Even TMEM182 plays important roles in adipogenesis, myogenesis, and glaucoma, however, its working mechanisms were still unknown." (PMID 30893332, 2019). "No phenotypes with a direct functional connection to TMEM182 have been reported, but its expression in adipocytes and its potential role in glaucoma have been explored." (PMID 24903457, 2014).
Obesity (1 paper, 2014). Accumulation of substantial excess body fat. "In conclusion, this genome-wide screen for BP-associated genes, which considered interaction between SNPs and obesity-related anthropometric measures, identified a genetic variant in East-Asian populations near TMEM182 that may influence BP." (PMID 24903457, 2014).
oral cancer (1 paper, 2019). "Therefore, TNF-α/miR-450a/TMEM182 signaling axis may be a novel potential target for clinical intervention in oral cancer." (PMID 30893332, 2019).
tumor (4 papers, 2017 to 2022). "Upregulation of miR-450a could reduce cellular adhesion to matrix by targeting TMEM182 and enhance tumor invasion." (PMID 30893332, 2019). "TNF-α is a known tumor motility promoter, correlating with increased metastasis rates in OSCC patients by mediating the expression of TMEM182 and activating the ERK1/2 pathway." (PMID 36143043, 2022). "Other MS loci display marked cancer-type specificity, for example, MSI events within the 5′ UTR region of ZNF738, C10orf140, ZNF271 and RAB28 are specific to COAD tumours, whereas those in EBP, TMEM182, MIR567 and MEIS1 are absent or substantially depleted in STAD compared to COAD and UCEC tumours." (PMID 28585546, 2017).
TMEM182 also shares sentences with these, for which no sentence is quoted: cancer (1 paper); migraine (1); oral squamous cell carcinoma (1); Stillbirth (1).